STAT6 (signal transducer and activator of transcription 6)
Diseases named in the same sentence as STAT6 in open-access papers (continued):
Sharing a sentence is not in itself a finding about the gene and the disease.
liver cancer (8 papers, 2017 to 2025). An epithelial or non-epithelial malignant neoplasm that arises from the liver. "STAT6 deficiency also corrected liver injury and inflammation induced by alpha-galactosylceramide, a specific agonist for invariant natural killer T (iNKT) cells evaluated in the context of treatment for liver cancer." (PMID 41409600, 2025). "For example, betulinic acid inhibits STAT6 phosphorylation and decreases M2 polarization in the microenvironment of liver cancer, resulting in antitumoral effect." (PMID 41409600, 2025). "In the macrophage THP-1 cell line co-cultured with the liver cancer cell line H22, lncRNA-Colorectal Neoplasia Differentially Expressed (CRNDE) overexpression leads to STAT6 upregulation." (PMID 41409600, 2025). "For example, high expression of lncRNA CRNDE activates JAK1 and STAT6 expression and upregulates the phospho-STAT6-dependent expression of CD163 and M2 polarization in liver cancer." (PMID 36263199, 2022).
Sepsis (8 papers, 2015 to 2025). Sepsis is defined as life-threatening organ dysfunction caused by a dysregulated host response to infection. "Herein we show that genetic deletion of ST2 and STAT6 prevents the expansion of Foxp3+ Treg cell population in sepsis-surviving mice, concomitant with a marked improvement in the survival rate after secondary pneumonia induced by L. pneumophila infection." (PMID 28374774, 2017). "Accordingly, IL-4 stimulation induced higher STAT6 phosphorylation in peritoneal macrophages from sepsis-surviving WT mice than that observed in the macrophages from naive mice, an effect that was abrogated in macrophages from sepsis-surviving Il1rl1−/− mice." (PMID 28374774, 2017). "Accordingly, arginase activity assessed indirectly by urea production was considerably lower in the peritoneal lavage and BAL fluids from sepsis-surviving Il1rl1−/− and Stat6−/− mice than in those from the WT controls." (PMID 28374774, 2017). "Collectively, these data indicate that IL-33/ST2 and IL-4/IL-13/STAT6 signalling are required for the expansion of Treg cells in sepsis-surviving mice, linking IL-10-secreting M2 macrophage in this process." (PMID 28374774, 2017). "However, sepsis-surviving Stat6−/− mice were more resistant to subsequent infection with L. pneumophila." (PMID 28374774, 2017). "Since ST2 and STAT6 signalling were required for the differentiation of M2 macrophages in sepsis survivors, we hypothesized that M2 macrophages might contribute to the expansion Treg cell population in sepsis-surviving mice." (PMID 28374774, 2017). "Since ST2 and STAT6 signalling were critical to induce M2 polarization in sepsis-surviving mice, we examined whether M2 macrophages might induce the generation of Treg cells." (PMID 28374774, 2017). "Moreover, sepsis-surviving Stat6−/− mice showed significantly lower bacterial burdens in the lungs and spleen than those of the WT mice after L. pneumophila challenge." (PMID 28374774, 2017). "Moreover, production of IGF-1 protein in the lung was also reduced in the lungs of sepsis-surviving Il1rl1−/− or Stat6−/− mice." (PMID 28374774, 2017). "However, STAT6-deficiency did not reduce the amount of IL-33 in the lungs of sepsis-surviving mice, again indicating that the function of IL-33 is upstream of type 2 cytokines in the present system." (PMID 28374774, 2017). "Importantly, macrophages recovered from sepsis-surviving Il1rl1−/− and Stat6−/− mice harboured significantly fewer bacteria than macrophages from sepsis-surviving WT mice, showing the key role of ST2 and STAT6 in the impaired bactericidal activity of the macrophage from sepsis-surviving mice." (PMID 28374774, 2017). "Next, to confirm that the IL4 signaling pathway does not play a substantial role in the protection conferred by α-GalCer against sepsis, we employed AS1517499, an inhibitor of the STAT6 transcription factor that is critical for IL4 signaling." (PMID 39355237, 2024). "Treatment with a STAT6 inhibitor was unable to modulate disease progression, indicating that IL4 signaling did not significantly affect iNKT cell-mediated protection against sepsis." (PMID 39355237, 2024). "In contrast, the production of IL-10 in the lungs of Il1rl1−/− and Stat6−/− mice was markedly reduced at day 15 after CLP, suggesting that type 2 cytokines and IL-33 are involved in the production of IL-10 in sepsis-surviving mice." (PMID 28374774, 2017). "Instead, we found that ST2 and STAT6 signalling were required for M2 polarization since the expression of CD206 was not increased in peritoneal macrophages from sepsis-surviving Il1rl1−/− or Stat6−/− mice." (PMID 28374774, 2017). "During late-stage sepsis, TIGIT-expressing Foxp3+ Tregs exhibit enhanced suppressive function dependent on the IL-33/ST2/STAT6/M2 macrophage axis, suggesting that IL-33 or anti-TIGIT therapy may represent a promising strategy for the treatment of immunosuppressive sepsis." (PMID 40806563, 2025).
Sepsis (continued). "Similar to findings obtained with sepsis-surviving Il1rl1−/− mice, the production of IL-4 and IL-13 was markedly reduced in the lungs of Stat6−/− mice on day 15 after CLP, indicating that these type 2 cytokines can induce their synthesis in a positive feedback loop in an STAT6-dependent manner." (PMID 28374774, 2017). "However, the frequency and the absolute number of Treg cells were not increased in the spleens of sepsis-surviving Il1rl1−/− or Stat6−/− mice." (PMID 28374774, 2017). "Moreover, adoptive transference of M2-polarized macrophages into sepsis-surviving mice lacking STAT6 markedly induces expansion of Treg cell population and increases susceptibility to secondary pneumonia induced by L. pneumophila." (PMID 28374774, 2017). "Conversely, sepsis-surviving mice lacking ST2 or STAT6 do not show polarization of M2-like macrophage, indicating that type 2 cytokines and IL-33 are critically involved in the polarization of M2 macrophages in sepsis-surviving mice." (PMID 28374774, 2017). "In sepsis, RELA, CEBPB, NFKBIA, STAT6, IRF8 and SPI1 were downregulated, with no significant change in NFKB1, JUN and GLI1." (PMID 39444551, 2024).
dermatitis (7 papers, 2020 to 2025). An inflammatory process affecting the skin. "Whereas, some studies showed that the T alleles of STAT6 rs167769 could increase STAT6 promoter activity, which further increases the STAT6 signaling axis in dermatitis." (PMID 32283835, 2020). "AD appears to be characterized by skin inflammation, barrier dysfunction, and chronic pruritus, which are all attributable to excessive activation of the IL-13/IL-4‒JAK‒STAT6/STAT3 axis and its associated immune reaction." (PMID 33233866, 2020). "In addition, JAK-activated STAT6 stimulates inflammatory chemokine expression in keratinocytes, exacerbating skin inflammation." (PMID 40806199, 2025). "In the absence of STAT6, required for signaling through the IL4 and IL13 receptor, these mice had undetectable IgE, but developed a similar dermatitis indicating that the IgE was not necessary for the development of the dermatitis." (PMID 32687504, 2020).
food allergy (7 papers, 2020 to 2025). Gastrointestinal disturbances, skin eruptions, or shock due to allergic reactions to allergens in food. "Clinical studies indicate that two STAT6 gene variants, rs324015 and rs1059513, are significantly associated with food allergy and more severe allergic symptoms." (PMID 37469874, 2023). "Her mother had a history of severe food allergies and recurrent respiratory infections, which are common symptoms of STAT6 GOF disease." (PMID 40502541, 2025). "In addition, three articles have supported the relevance of this variant in food allergy, which is consistent with the trend observed in our work towards a higher prevalence of food allergy in patients with the STAT6 g.18453G>C (rs12368672) C/C genotype compared to the G/G and G/C genotypes." (PMID 38612496, 2024). "The patient had all the hallmarks of STAT6 GOF disease, early-onset severe atopic dermatitis, food allergies, and elevated absolute eosinophil counts and serum IgE levels." (PMID 40502541, 2025). "Another study that examined the factors required for induction of IL-9 producing MMC9 cells in a food allergy model illustrated the essential requirement for STAT6 in the development of these cells, although STAT6 is not required for mast cell development in general." (PMID 35387064, 2021).
pancreatic cancer (7 papers, 2005 to 2025). "The mechanistic basis of STAT6-stimulated proliferation has recently been elucidated in pancreatic cancer." (PMID 34769439, 2021). "All human pancreatic cancer cells tested expressed various levels of Stat1, Stat3, and Stat6 proteins." (PMID 15714203, 2005). "A very faint Stat3 band was also detectable in the other cell lines after a long exposure; Stat6 (120 kDa) was also expressed in pancreatic cancer cells at various levels, with the highest levels found in COLO-357 cells." (PMID 15714203, 2005). "As expected, IL-13 induced STAT6 phosphorylation in IL-13Rα2-negative pancreatic cancer cell lines." (PMID 21477288, 2011). "At first, we examined whether pancreatic cancer cell lines express Stat1, Stat3, and Stat6." (PMID 15714203, 2005). "On the contrary, in pancreatic cancer, up-regulation of SOX21 by STAT6-activated SOX21-AS promotes cancer cells malignancy." (PMID 40141294, 2025). "Exogenous IL-13 was shown to induce the expression of MMPs including MMP-9, MMP-12, and MMP-14, which were related to pancreatic cancer invasion in IL-13Rα2-positive pancreatic cancer cells independent of STAT6 phosphorylation." (PMID 33804263, 2021). "Pancreatic cancer cells were determined to express the transcription factors STAT1, STAT3, and STAT6 at various levels, while Stat3 phosphorylation was enhanced in response to IL-4 stimulation, and STAT6 nuclear translocation was increased after exposure to IL4." (PMID 33804263, 2021).
rheumatoid arthritis (7 papers, 2016 to 2025). A chronic, systemic autoimmune disorder characterized by inflammation in the synovial membranes and articular surfaces. "STAT1 and STAT6 have been reported to be increasingly expressed in rheumatoid arthritis, wherein they mediate the secretion of inflammatory mediators." (PMID 32290603, 2020). "Genetic polymorphisms of IL-4 and its signaling downstream element, STAT6, are also related to systemic lupus erythematosus (SLE) in humans, and increased plasma IL-4 can be detected in patients with SLE or rheumatoid arthritis." (PMID 29184551, 2017).
spindle cell neoplasm (7 papers, 2021 to 2026). A benign or malignant neoplasm characterized by the presence of neoplastic spindle cells. "Given the histological overlap with other spindle cell neoplasms, integrating STAT6 into the diagnostic algorithm improves accuracy and reduces misclassification." (PMID 40308427, 2025). "Histopathological examination demonstrated a spindle-cell neoplasm with the typical "patternless pattern," and immunohistochemistry confirmed nuclear STAT6 positivity, establishing the diagnosis of SFT." (PMID 42040513, 2026). "These tumors are generally positive for CD34, STAT6, and other markers that help differentiate them from other spindle cell neoplasms." (PMID 40861561, 2025). "Histologically, they exhibit a staghorn vascular pattern and express markers including CD34 and STAT6, helping to distinguish them from other spindle cell tumors." (PMID 41140989, 2025). "It illustrates the utility of immunohistochemical markers, particularly STAT6, and fusion analysis in diagnosing rare spindle-cell tumors in the genitourinary tract." (PMID 39583332, 2024). "Histopathological examination of needle-core biopsies showed spindle cell neoplasm with small and fusiform cells, strongly expressing signal transducer and activator of transcription 6 (STAT6) with a ramifying vascular network." (PMID 34833370, 2021). "As previously stated, immunohistochemistry findings confirmed the recurrent tumor as a spindle cell neoplasm, with immunopositivity for CD31 (80-90%), CD34 (>90%), ERG (5-10%), and STAT6 (>90%)." (PMID 40861561, 2025). "Immunohistochemistry confirmed the recurrent tumor as a spindle cell neoplasm, with immunopositivity for CD31 (80-90%), CD34 (>90%), ERG (5-10%), and STAT6 (>90%)." (PMID 40861561, 2025). "Histopathology revealed spindle cell tumor embedded in myxohyaline stroma along with hyalinized vascular channels demonstrating IHC positivity for CD34 and STAT6." (PMID 37533000, 2023).
systemic lupus erythematosus (7 papers, 2013 to 2025). An autoimmune multi-organ disease typically associated with vasculopathy and autoantibody production. "Our data collectively suggests that IL-2 induces IL-13, IL-5, and IFN-γ expression in lupus CD8+ T cells via STAT6-GATA-3 dependent mechanisms in contrast to the Treg differentiation in which IL-2-STAT5 axis plays a more essential role." (PMID 33763079, 2021). "On the other hand, IL-2 expanded IL-13-producing CD8+ T cells that also expressed IL-5 and IFN-γ in lupus patients via a signaling pathway likely involving the activation of STAT6-GATA-3 axis, but not STAT5." (PMID 33763079, 2021). "In addition, IL-2 expanded the IL-13-producing lupus CD8+ T cells that also expressed IL-5 and IFN-γ in association with STAT6 phosphorylation and GATA-3 expression, but not with STAT5 phosphorylation." (PMID 33763079, 2021). "Therefore, NEAT1 promotes Th2 cell activation through STAT6, supporting the observation that NEAT1 expression is induced in the PBMCs of systemic lupus erythematosus (SLE), which is primarily influenced by a Th2-mediated immune response." (PMID 40362651, 2025).
Autoimmunity (6 papers, 2015 to 2025). The occurrence of an immune reaction against the organism's own cells or tissues. "Among those, the LRP1/STAT6 novel mutation has the strongest case for being categorised as potentially causative of MAS given the presence of intriguing patterns of functional interaction with other major genes shaping autoimmunity." (PMID 26031516, 2015). "This is of special relevance in autoimmunity because STAT6 is involved in the polarization of naïve T cells to Th2 effector cells, and the activation of STAT6 leads to the expression of Th2 cytokines such as IL-4 and IL-13." (PMID 37107175, 2023). "It is attractive to speculate that the suppressive role of STAT3 and STAT6 is important to prevent NK-cell overshoots and autoimmunity." (PMID 28149296, 2016). "LRP1/STAT6 disclosed the strongest plausibility for autoimmunity." (PMID 26031516, 2015). "In addition to the genes above, it is also clear that this approach identified well known genes associated with autoimmunity within the exome variant data of these patients, which in this case are ICA1 and STAT6 (encoded by the same variant as LRP1)." (PMID 26031516, 2015). "Along that line, we previously showed that STAT6 deletion converts the LatY136F DLSP into a type 1 inflammatory and autoimmune disorder involving Th1 and CD8+ effector T cells." (PMID 37624388, 2023). "Further, ICA1 and STAT6 were also closely related to AIRE and IRF5, two very well known autoimmunity genes." (PMID 26031516, 2015). "These autoimmunity in scurfy mice is dependent on STAT6 pathway, a JAK-STAT signaling pathway known to be important in Th2 immunity, and Tfh cells are also decreased in the lymph nodes and spleen of Stat6–/– scurfy mice." (PMID 37138879, 2023).
Granuloma (6 papers, 2014 to 2025). A compact, organized collection of mature mononuclear phagocytes, which may be but is not necessarily accompanied by accessory features such as necrosis. "Th2 cytokines also have an important role in fibrogenesis, as demonstrated by the fact that mice deficient in STAT6 have granulomas with smaller area and less collagen content." (PMID 33815321, 2021). "The concurrent expression of Acetyl-H3K9, Chi3l1, CSF1R, IL4R, TGFß, and Jak3/Stat6 in granulomas of cardiac sarcoidosis promotes the polarization of macrophages toward the M2 phenotype, facilitating anti-inflammatory conditions and driving fibrotic processes." (PMID 40521183, 2025). "The concurrent expression of Acetyl-H3K9, Chi3l1, CSF1R, IL4R, TGFß, and Jak3/Stat6 in granulomas of CS further reinforces macrophages towards M2 polarization, thereby leading to anti-inflammatory states and fibrosis." (PMID 40521183, 2025). "Additionally, we observed an enhanced expression of IL13Rα1, Jak3, and STAT6 in macrophages within CS granulomas and the increased phosphorylation of Jak3 and STAT6 are indicative of an activation of anti-inflammatory IL4/IL13 signaling pathways." (PMID 40521183, 2025). "In histological staining of granuloma regions, Relm-α was abundantly expressed in IL-4c-treated Mac-STAT6 mice, more prominent than in the PBS or STAT6ko controls and co-staining with CD68 and DAPI confirmed Relm-α expression in AAMs with similar frequency in Mac-STAT6 and WT mice." (PMID 37018382, 2023). "Furthermore, since nuclear localized NF-κB, phospho-STAT-1 and phospho-STAT-6 were detected in granuloma FCMs, activators of the pathways leading to M1 and M2 polarization also existed in adequate quantities in the presence or absence of T or B lymphocytes." (PMID 25389425, 2014). "Importantly, although previous studies have confirmed the involvement of these receptors in granulomas, our data reveal a novel aspect: the spatial expression pattern shows that activated JAK3/STAT6 signaling largely overlaps with IL4R/IL13R expression but is conspicuously excluded from giant cells." (PMID 40521183, 2025).
migraine (6 papers, 2020 to 2025). "STAT6 (PoPS Score Overall: 3.00, MA: 0.71, MO: 2.29) demonstrated consistent associations with immune modulation in both Overall migraine and MO, while also showing weaker links to MA." (PMID 40826382, 2025). "Through our analysis of two different brain proteomes using PWAS and TWAS of brain and vascular transcriptomes, we identified three potential causal genes for migraine (STAT6, ICA1L, and TREX1)." (PMID 37592229, 2023). "We found significant associations with migraine for 47 genes, with the strongest association for STAT6 (P = 1.24 × 10−23), followed by UFL1 (P = 7.26 × 10−19), and FHL5 (P = 1.25 × 10−18)." (PMID 34294844, 2021). "We also observed that the expression of STAT6 in whole blood is significantly associated with an increased risk of migraine, while its expression in CNS and vascular tissues is significantly associated with a decreased risk of migraine." (PMID 37592229, 2023). "This suggests that the effect of STAT6 on the risk of developing migraine may be tissue-specific." (PMID 37592229, 2023). "In our study, substantially elevated SNP-based heritability and replicable top hits in risk loci of PRDM16, FHL5, ASTN2, STAT6/LRP1, SLC24A3 genes were found among migraine-first patients." (PMID 39333847, 2024). "While, four of these (ICA1L, TREX1, STAT6, and UFL1) have been previously reported in association with migraine." (PMID 37592229, 2023). "The STAT6 gene provides novel insights into migraine’s neuroimmune mechanisms." (PMID 40826382, 2025). "It is hypothesized that STAT6 may contribute to the activation of the trigeminal vascular system, a process that can trigger an inflammatory response and sustain the state of migraine." (PMID 37592229, 2023). "Methodologically, FUSION demonstrated the highest yield, identifying 62 genes across subtypes, with 48 in Overall migraine, 14 in MA, and 18 in MO, supported by robust multi-method validation (e.g., PHACTR1, STAT6)." (PMID 40826382, 2025). "Five genes, including ICA1L, TREX1, STAT6, UFL1, and B3GNT8, showed significant correlation with migraine in both the proteome and transcriptome." (PMID 37592229, 2023).